KLF4 (KLF transcription factor 4)
Diseases named in the same sentence as KLF4 in open-access papers (continued):
Sharing a sentence is not in itself a finding about the gene and the disease.
tumor (continued). "Similarly as observed for KLF4, transient inhibition of endogenous miR-206 by anti-miR-206 transfection suppressed tumor initiation in vivo but did not alter the in vitro proliferation or the MaCSC abundance." (PMID 26053033, 2015). "Moreover, it has been reported that the absence of KLF4 promotes tumor development in mice treated with carcinogenic agents." (PMID 25181544, 2014). "KLF4 staining was observed in the cytoplasm of non-tumorous hepatocytes and tumor cells." (PMID 24897024, 2014). "However, on the other hand, recent studies demonstrated that rather than an oncogene, Klf4 serves as an inhibitor for tumor cell growth and migration 85,87,88." (PMID 25116380, 2014). "C-MYC may function as an oncogene and OCT4, KLF4, NANOG and SOX2 as tumor suppressors." (PMID 21982273, 2011). "Thus, Klf4 and Runx1 depletions are sufficient to reverse and blunt Smad4 function in liver and lung metastases, respectively, which demonstrates that KLF4 facilitates Smad4’s tumor-suppressive activity in the liver and RUNX1 contributes to Smad4’s tumor-promoting activity in the lungs." (PMID 40999053, 2025). "Given that KLF4 has been shown to significantly influence CD8+ T cell proliferation and differentiation in normal T cell biology, it raises the question of whether KLF4 similarly affects CD8+ T cell differentiation in the tumor microenvironment (TME), thereby impacting anti-tumor efficacy." (PMID 39995670, 2025). "However, the evidence for anti- or pro-tumor effects of KLF4 is not conclusive." (PMID 37031197, 2023). "However, except that the effect of SUMOylation of KLF4 on promotion of M2 polarization is limited in RAW264.7 cells, the regulatory role of protein SUMOylation or de‐SUMOylation has been less studied during the reprogramming process of macrophage polarity towards ‘pro‐tumor’ M2 subtype." (PMID 33932085, 2022). "Our in vitro and in vivo data suggest that overexpression of DUB3 and/or KLF4 may activate the DUB3/KLF4 loop to prevent tumor growth and chemoresistance, whereas knockdown of DUB3 and/or KLF4 may block the DUB3/KLF4 loop to facilitate tumor growth and chemoresistance in HCC." (PMID 35383144, 2022). "In addition, KLF4 also displayed negative correlation with tumor purity in both LUAD and LUSC." (PMID 34440860, 2021). "Compared to tumors from mice that were not exposed to Paclitaxel treatment (primary tumor), tumors from recurrent disease after treatment with Paclitaxel (early recurrent tumor) had higher levels of genes associated with stemness such as ALDH1, KLF4, MYD88, NANOG, and OCT-4." (PMID 24403249, 2013). "In contrast, other tumor areas exhibiting high expression of TMPRSS11B together with BSG and SLC16A1 were largely negative for KLF4 expression." (PMID 40508207, 2025). "KLF4, SOX2, and NANOG had low expressions in tumor tissue compared with its adjacent non-malignant (NM) counterpart, while no significant changes were found for c-MYC and OCT4 gene expressions." (PMID 41463190, 2025). "Tumours from HCT116‐KOs cells did not present any statistically significant change in SOX2 expression, but they shared a significant reduction in KLF4 expression." (PMID 34623757, 2022). "Nestin, KLF4, ALDH1, EPCAM as well as ABCG2 expression was incongruous, with no clear relation to the four different parental tumor groups." (PMID 33800955, 2021). "Accordingly, our in vivo xenograft studies demonstrated that with KLF4 overexpression, EpCAM−/CD133− non-stem cells attained an in vivo tumor-forming ability comparable to EpCAM+/CD133+ LCSCs." (PMID 32408542, 2020). "According to univariate and multivariate analysis, we concluded KLF4 was an independent prognostic factor regardless of HCC stage, tumor differentiation, and tumor size." (PMID 32756012, 2020). "It has been suggested that KLF4 expression is inversely correlated with CA tumor grade, with HGCA producing less KLF4 than LGCA tumors, and the highest expression seen in the normal colon adjacent to tumors." (PMID 32428045, 2020).
tumor (continued). "A negative correlation was reported in between KLF4 and LDHA expression; KLF4 under expression and LDHA overexpression were clinically correlated with disease stage and tumor differentiation in patient samples." (PMID 31146503, 2019). "Our statistical analysis showed that there is a negative correlation between KLF4 and TWIST expression in normal-appearing mucosa and tumor tissues (P < 0.001)." (PMID 32566755, 2019). "Increased T cell numbers in Hi-Myc tumors forming in Klf4(f/f);Lys-Cre mice is potentially related to a change in the composition of the ECM generated by CD11b+ tumor myeloid cells lacking Klf4." (PMID 29324844, 2018). "ALDH1 positive cells from 5-8F and CNE-2 cell lines induced tumour growth, contained higher percentage of SP subpopulation and had higher levels of OCT4, BMI1, KLF4 and SOX2 transcripts than ALDH1 negative cells." (PMID 28959019, 2017). "Although we have not performed methods to determine the tumor-initiating capacities of CD133+ cells in vivo, the importance of CD133 in CSCs has widely been confirmed As KLF4 plays a key role in the induction and maintenance of stem cells." (PMID 23418515, 2013). "Alternatively, OTUD1 may inhibit the proliferation, migration, and invasion of NSCLC cells by deubiquitinating and stabilizing the tumor suppressors KLF4 and FHL1, but the authors did not delve into the ubiquitination site of KLF4." (PMID 41050073, 2025). "Interestingly, the response to APTO253 was restricted to tumor cells, whereas lymphocytes from healthy donors did not up-regulate MICA or KLF4." (PMID 37143070, 2023). "We then analyzed the KLF4 and EpCAM expressions on tumor biopsies collected from 50 HCC patients and also identified a correlation between KLF4 and the EpCAM protein expression in HCC patients, independent of the tumor stage and differentiation status." (PMID 32408542, 2020). "Additionally, we identified a correlation between the KLF4 and EpCAM protein expressions in human HCC tissues independent of the tumor stage and differentiation status." (PMID 32408542, 2020). "We analyzed the significance among normal and tumor tissues, and we found that only OCT4 (p value < 0.0001) and SOX2 (p value = 0.0014) had higher expression in tumor tissues, not so for KLF4 (p value = 0.0610), C-MYC (p value = 0.0900), or NANOG (p value = 0.0969)." (PMID 31885625, 2019). "A2BR knockdown did not affect tumor growth rate or sensitivity to paclitaxel, but attenuated paclitaxel-mediated increases of the percentage of ALDH+ cells, the number of mammosphere-forming cells, and the mRNA expression of pluripotency factors NANOG, SOX2, and KLF4." (PMID 35401817, 2022).
cancer (643 papers, 2006 to 2026). A tumor composed of atypical neoplastic, often pleomorphic cells that invade other tissues. "Beyond stem cell biology, KLF4 has been implicated in the pathogenesis of inflammation and cancer, exhibiting a context‐dependent and sometimes paradoxical role." (PMID 41532367, 2026). "One such study identified that KLF4 binds the promoter of human telomerase reverse transcriptase (hTERT), thereby activating telomerase, which is a hallmark of cancer." (PMID 40552304, 2025). "While KLF4 has been implicated in many cancers, the significance of alterations in KLF4 expression across a broad range of tumors requires further examination." (PMID 40299916, 2025). "KLF4 is a transcription factor linked to cancer cell stemness, facilitating self-renewal and drug resistance in cancer cells." (PMID 40710326, 2025). "Krüppel-like factor 4 (KLF4) is a zinc-finger transcription factor widely involved in cell reprogramming towards pluripotency and associated with cancers of different histological origin." (PMID 40863723, 2025). "Herein, a systematic analysis of KLF4 genetic alterations revealed the mutation, amplification, and deletion frequencies across different cancer types." (PMID 40299916, 2025). "The results of the current study show that KLF4 is associated with cancer prognosis and immune infiltration across several types of cancers, which is consistent with the findings of recent studies." (PMID 40299916, 2025). "These modifications affect KLF4’s stability and activity, and mutations at these sites alter its function in specific cancer contexts." (PMID 39995670, 2025). "This is underscored by the fact that in SLC16A1/BSG-expressing but TMPRSS11B-deficient cancer cells, the nuclear expression levels of reprogramming factors such as KLF4 are elevated, a condition identified as a hallmark of reverse Warburg cells." (PMID 40508207, 2025). "The results demonstrated that KLF4 expression is significantly associated with clinical stage in six of the examined cancer types: BRCA (p = 0.0384), KIRC (p = 2.68e − 07), KIRP (p = 1.02e − 06), PAAD (p = 0.0126), TGCT (p = 0.0224), and THCA (p = 0.0393)." (PMID 40299916, 2025). "In this line of thinking for EBVaGC, MUC1-C was necessary for upregulation of the (i) SOX2 and KLF4 genes, which are linked to cancer progression, and (ii) NOTCH genes that drive stemness." (PMID 40764753, 2025). "The TFs captured in Fig F in S1 Text also have known associations with cancer (e.g., KLF4 and PAX2)." (PMID 38206988, 2024). "As a pluripotent transcription factor for cancer stem cells, KLF4 was intimately implicated in cancer drug resistance." (PMID 38924680, 2024). "Despite the lack of understanding regardingthe mechanisms causing these differences, available evidence suggeststhat KLF4 is a crucial factor in cancer and emphasizes the necessityof further elucidating its specific role in CSCs." (PMID 37636966, 2023). "In other cancers, high expression of KLF4 was associated with increased OS in BC (HR =0.49, 95% CI: 0.33–0.72) and head and neck tumours (HR =0.41, 95% CI: 0.23–0.75)." (PMID 35177016, 2022). "Previous research groups in concert with our experimental data revealed that MET is associated with the (re)-activation of KLF4 and a proliferative cell growth of R(C)T-treated cancer cells." (PMID 36289744, 2022). "Rather, a decrease or loss of KLF4 expression was observed in the late stage of cancer and proposed as a predictor for poor survival of patients." (PMID 36661504, 2022). "Dysregulation of GLUT1 is associated with numerous cancers, suggesting that dysregulation of KLF4 can have potentially harmful effects." (PMID 33917010, 2021). "KLF4 associates with the patient survival metrics across multiple cancers in a context-specific manner, highlighting the complex association of EMP with patient survival." (PMID 34680284, 2021). "KLF4 is an important mediator of pluripotent stemness which is associated with metastasis and chemo-resistance in cancer." (PMID 33726845, 2021).
cancer (continued). "Of those, KLF4 was shown to be particularly downregulated (log2(fc) = − 3.37; p = 0.00) and has been demonstrated to be associated with tumorigenesis and cancer stemness." (PMID 33726845, 2021). "YY1 was also shown to promote the expression of the stemness factor KLF4 and has been implicated in promoting the expression of stemness factors in cancer stem cells." (PMID 34115613, 2021). "More and more information is available about upstream regulators, downstream targets and signaling pathways associated with the involvement of KLF4 in cancer." (PMID 33266506, 2020). "Meanwhile, the expression of cancer stem cell associated proteins, such as Sox2, Nanog, Klf4 and Myc, were also abated at different levels by AR-42 at 1 μM." (PMID 31897232, 2020). "Irrespective, both these models indicate that complete KLF4 loss in utero is incompatible with life, and concomitant with its role in cancer progression, strongly indicate that this protein is a key element of cellular integrity." (PMID 33266506, 2020). "Although miR-7-5p was predicted to have approximately 112 downstream target genes, we discovered that KLF4 is associated with cancer stem cells and was ranked as a downstream target gene of miR-7-5p." (PMID 33052880, 2020). "In BRCA1‐proficient TNBC cells, we observed the same result—that elevated wild‐type KLF4 drastically promotes cancer cell survival in the presence of olaparib, whereas little effect was observed for expression of the PARylation‐deficient KLF4 mutant." (PMID 33231937, 2020). "Previously, we demonstrated that transgenic overexpression of Klf4 within esophageal keratinocytes activates NFκB signaling, which is associated with the development numerous inflammatory diseases and cancers, resulting in inflammation-mediated ESCC." (PMID 30998758, 2019). "Inactivation of KLF4 has been reported to be associated with the growth and survival of various cancer cells." (PMID 30952833, 2019). "Now, in the case of cancer, there is evidence that promoter hypermethylation and deletion mutation in KLF4 gene can reduce or eliminate the expression of this gene." (PMID 31724937, 2019). "Here, we investigated the mechanisms underlying how PLAC8 promotes cancer progression and explored the effects of altered KLF4 expression on PLAC8 in LC cells." (PMID 29789534, 2018). "A list of candidate targets of miR-7 were obtained, and among them, KLF-4 appears to be a promising target as it is implicated in the pathology of cancer." (PMID 28239300, 2017). "Here, we define WNT5A, a non-canonical Wnt ligand implicated in epithelial differentiation, repair, and cancer, as a direct transcriptional target that is activated by KLF4 in squamous epithelial cells." (PMID 27184424, 2016). "KLF4 expression is decreased in many types of carcinomas in advanced stage and the loss of expression initiates epithelial-mesenchymal transition of carcinoma cells that strongly stimulates the progression." (PMID 26847634, 2016). "KLF4 has been shown to regulate cell proliferation and differentiation, its role has been extensively investigated in several human cancers by using gain- and loss-of-function approaches." (PMID 25137052, 2014). "Among the PRCa genes expressed at the protein level are transcriptional regulators (Hdac2 and Hmga2), cancer-linked genes (Klf4 and Kit), and genes involved in glycolysis and pyruvate metabolism (Hk1, Eno2, and Pck2)." (PMID 22305566, 2012). "Moreover, this reduction in KLF4 expression in cancer cells is believed to be caused by genetic and epigenetic alterations." (PMID 40299916, 2025).
cancer (continued). "Kruppel-like factor 4 (KLF4), a zinc finger transcription factor and member of the Spl/Kruppel-like zinc finger family, is pivotal in regulating cell proliferation, differentiation, and apoptosis, and it is implicated in various diseases, including cancer." (PMID 40722703, 2025). "KLF4 expression is also strongly associated with immune-related gene expression in various cancers and may play a crucial role as a prognostic biomarker for different cancers and possible therapeutic target across several cancer types." (PMID 40299916, 2025). "Additionally, KLF4 expression and cancer-associated fibroblast infiltration was found to be positively correlated in BRCA, BRCA-LumA, LIHC, and PCPG, while negatively correlated with HNSC, HNSC-HPV-, STAD and TGCT, based on all or most algorithms." (PMID 40299916, 2025). "In addition to ESCs, KLF4 promotes self-renewal in tissue-specific stem cells (e.g., embryo, intestine, skin) and cancer-associated stem cells." (PMID 40589762, 2025). "Furthermore, aberrant KLF4 expression has been associated with various cancers, including cancer stem cells." (PMID 40299916, 2025). "Whether the sustained increase of KLF4 in cancers, especially in early lesions of PDA is associated with the mutations of PEST remains unknown." (PMID 37031197, 2023). "The underlying mechanism of KLF4 downregulation in cancer remains to be elucidated." (PMID 35177016, 2022). "In addition, expression of OCT4, Nanog, SOX2, and Myc was reported in CSCs of various cancers, and their expressions were associated with the prognosis of the patients, although an oncogenic role of KLF4 appeared to be dependent on tissues." (PMID 36661504, 2022). "KLF4 expression is highly associated with human OS cancer stemness." (PMID 36499521, 2022). "The fact that KLF4 is stemness factor suggests the association of KLF4 with cancer stem cells." (PMID 35008527, 2021). "Kruppel-like factor 4 (KLF4) has been shown to be associated with DDP resistance in some cancers." (PMID 34778078, 2021). "KLF4, member of the Kruppel-like factor (KLFs) family of gene regulatory proteins, implicated in the regulation of cell-fate, differentiation, and migration, as well as cancer metastasis." (PMID 32819319, 2020). "The reduced expression of KLF4 is associated with the molecular features of aggressive cancers." (PMID 33266506, 2020). "Further, systematic epigenomic analysis of OIP5-AS1 promoter revealed binding motifs for MYC, NANOG and KLF4 suggesting that OIP5-AS1 could be transactivated by stemness-associated transcription factors in cancer." (PMID 29728583, 2018). "These included genes involved in cell death and survival processes (BCLAF1, CFLAR, CASP1, and XIAP), genes associated with proliferation-driving transcription or cancer (KLF4, LEF1, SOX4, ID3), and genes associated with inflammation (CD28, CCR7, CX3CR1 and IFNG)." (PMID 28407008, 2017). "We also noted that KLF4 and miR-1 levels were negatively associated with cancer grading." (PMID 27991915, 2016). "Moreover, clinical evidences indicated that inactivation of KLF4 was also associated with cancer progression and poor prognosis in some type of cancers." (PMID 27531889, 2016). "The loss of KLF4 expression contributed to carcinogenesis in several cancer types." (PMID 23861801, 2013). "On the other hand, KLF4 encodes a transcription factor that is essential for inducing pluripotency in stem cells (or iPS; when overexpressed with other factors) and maintaining cancer stem cells." (PMID 22701625, 2012). "For example, the four transcription factors commonly utilized in iPSC reprogramming Sox2, Oct4, Nanog, and Klf4 have been linked to carcinogenesis, increased cancer malignancy and tumor drug resistance and are overexpressed in many cancers and cancer stem cells." (PMID 22919402, 2012).